ESR1 (estrogen receptor 1)
Diseases named in the same sentence as ESR1 in open-access papers (continued):
Sharing a sentence is not in itself a finding about the gene and the disease.
cancer (continued). "In luminal A cancer, the hypomethylation enhances the commitment of luminal lineage at key lineage-specific markers (GATA3, ESR1, FOXA1)." (PMID 31529022, 2020). "In common with other members of the nuclear receptor family, the ESR1 and ESR2 genes are subject to alternative splicing with both C terminal and exon-skipping isoforms identified in cancer cell lines and human tissues including the testis." (PMID 31778358, 2020). "The abnormal expressions of NOS2, DUOX2/DUOXA2, ESR1, EGFR, MYC, and AKT1, which are being discussed in this study, have been confirmed to be related to cancer." (PMID 33299870, 2020). "As ERα (ESR1) expression strongly parallels to the PR (PGR; Progesterone receptor), we next tried to assess the correlation between the ESR1, PGR, and FAM171A1 in published cell line datasets as well as in other cancer datasets." (PMID 30631046, 2019). "Screening the top 200 genes with monotonic expression against the Cancer Gene Census yielded a completely different set of six genes: HSP90AB1, ALDH2, ESR1, PPP2R1A, HIST1H4I, SEPT5." (PMID 31277598, 2019). "The miR-221-3p targets genes at early stage such as Annexin A1 (ANXA1), Cyclin Dependent Kinase Inhibitor 1B (CDKN1B), and multiple genes during advance-stage cancer such as CDKN1B, PTEN, Ring Finger Protein 20 (RNF20), Estrogen Receptor 1 (ESR1) and AKT3." (PMID 31756185, 2019). "In contrast, ESR1 is upregulated for survival by interacting with the transcriptionally active FOXO3 gene through Eleanors, which represents cancer robustness." (PMID 31439835, 2019). "Initially, we examined the growth of ESR1-expressing cells in the LAMPS model and determined the spatial relationship between the cancer cells and hepatocytes." (PMID 31171849, 2019). "Although the interaction between genes for growth (ESR1) and apoptosis (FOXO3) appeared contradictory at first, apoptotic activity is frequently enhanced in cancer, both in cultured cell lines and patient cells." (PMID 31439835, 2019). "We have shown that knock-down of HUGL1 in human mammary epithelial cells leads to upregulation of five transcripts that have been linked to cancer stem cells, side population (SP) cells, or increased invasion in cancers (ABCG2, MMP2, ESR1, THBS1 and KRT19)." (PMID 29361610, 2018). "Following effective silencing of NFE2L2 with siRNA to evaluate the impact on ESR1 expression, an elevated expression of ESR1 in the NFE2L2 downregulated cancer cell lines OVCAR3 (p = 0.003) and ES2 was noted (p < 0.001)." (PMID 30597961, 2018). "Despite several reports stating that AR expression is acquired in HER2/ESR1/PGR triple-negative cancers, here we show that a low percentage of these cancers express AR (~20%)." (PMID 30279965, 2018). "For instance, eIF2 signaling was among the top canonical pathways both for BPA and BPF; ESR1, MYCN or MYC were found as upstream regulators; and “cancer” as well as “organismal injury and abnormalities” were shared between the three products." (PMID 28628672, 2017). "The patient’s disease progressed, and after more than two years and numerous treatments, patient #2’s cancer was dominated by a new subclone (SC5), derived from the ESR1-mutant subclone SC4, with CCF of ~100%." (PMID 29093439, 2017). "We found alterations in DNA methylation related to age for 803 unique genes, most corresponding to coding genes known to be involved in cancer (e.g., TP73, CDKN1A and ESR1)." (PMID 29383109, 2017). "The gene expression levels of classic molecular cancer players such as fibroblast growth factor receptor (FGFR) 2, breast cancer (BRCA) 1, BRCA2 and estrogen receptor (ESR) 1 were evaluated." (PMID 28945747, 2017).
cancer (continued). "Above all, these results suggest that ESR1, FOXO1, CXCL12, and GNAO1 are involved in the pathogenesis of carcinoma by affecting cell division, complement activation, and protein activation cascades, which support our findings." (PMID 28302149, 2017). "We used primers for the gene sequences of UBB, ESR1 (for luminal or ER/PR+ cancer cells), HER2 and GRB7 (for HER2+ cancer cells), EPCAM, KRT7, KRT8, KRT18, and KRT19, all of which have been commonly discussed for the purpose of breast cancer diagnosis." (PMID 28936247, 2015). "ESR1, PGP9.5, HIC1 and VGF showed cancer specific methylation pattern in the training set explored, and we chose PGP9.5 and VGF to be further explored in an independent validation set." (PMID 24086249, 2013). "Transcript levels of growth factors and their receptors, such as VEGFA, MET, ESR1, EGFR, and HER2 were relatively undetectable in CTCs compared to cancer cell lines." (PMID 22586443, 2012). "In total, 1,009 genes were prone to hypermethylation by this analysis in at least one type of cancer, including a number reported to be frequently hypermethylated in cancer (for example, APC, DAPK1, ESR1, GSTP1, SFRP genes and HOX genes)." (PMID 23034185, 2012). "BPA may promote cervical carcinogenesis by interacting with ESR1 and PARP1 to regulate key cancer-related pathways." (PMID 41790626, 2026). "Notably, ERE was identified in the promoter of HES1 gene and both ESR1 and ESR2 were found to control HES1 expression in human cancer cells." (PMID 40506655, 2025). "Chronic exposure to CAP, however, may result in downregulation and internalization of ESR1, as well as TRPV1 stimulation of glucagon-like peptide 1 (GLP-1) expression, both of which downregulate GLUT expression, thereby starving cancer cells of glucose." (PMID 40003617, 2025). "This implies that estrogen-related mechanisms may affect the two cancers differently, although some genomic regions, including COMT, ESR1, and UGT1A1, impact both the risks of female DGC and OvC." (PMID 39862296, 2025). "This indicates that the expression level of ESR1 does not directly influence the proliferation and renewal capacity of cancer stem cells." (PMID 40342082, 2025). "Additionally, we examined the correlation between ESR1 and CDH5 across 34 different cancer types, which showed a significant positive correlation in most cancer types, including BLCA." (PMID 40665298, 2025). "Through serial-replating assay experiments, it was found that the expression level of ESR1 in the third generation had no apparent impact on the self-renewal ability of cancer stem cells." (PMID 40342082, 2025). "However, a significant (p < 0.05) positive correlation between ESR1 and S100A14 gene expression was found in Basal and Her2 cancer patients, but such a correlation was significantly (p < 0.05) negative in Luminal A and Luminal B patients." (PMID 39594999, 2024). "When the cells with high expression of ESR1 significantly reduced the activation of FOXA1 at the BIK promoter, preventing the expression of pro-apoptotic genes and eliminating the inhibitory effect of FOXA1 on cancer development." (PMID 38605023, 2024). "Our entire collection of cancer promoters was tested against each ESR1 construct in the presence or absence of 100 nM estradiol." (PMID 39013578, 2024). "In vitro, it was reported that ESR1 demethylation by 5-aza-2′-deoxycytidine (DAC) restored ERα expression in an ERα-negative cancer cell line." (PMID 39796024, 2024). "Comparing these genes to TCGA mutation data for over 30 tumor types showed that ESR1, EVC2, MYLK, PEAK1 and SLC2A4RG were not significantly mutated in any other human cancer type." (PMID 36140723, 2022).
cancer (continued). "We finally identified 4 mRNAs (AURKA, ASNS, ESR1 and SLC39A6), 3 miRNAs (has-let-7b-5p, has-mir-10a-5p and has-mir-17-5p), and 4 lncRNAs (SNHG16, CKMT2-AS1, NEAT1 and PSMA3-AS1), all of which have been reported in cancer." (PMID 36506097, 2022). "Interestingly, AR (or ESR1) silencing also blocked SG formation after ARPI (or ERPI) stress in prostate (and breast) cancer cells, highlighting a role for AR and ESR1 mRNA in triggering SGs when its receptor is antagonised." (PMID 34939643, 2022). "Another very prominent pathway in cancer is ERK/MAPK signaling (p = 3.47 × 10−2; ESR1, FYN, ITGA3, PIK3R3, PLA2G4A, PLA2G5, RPS6KA5), which is the core of the signaling network involved in regulating cell growth, development, and division and a target of many cancer therapeutics." (PMID 35106465, 2022). "As a downstream event of activated ESR1 signalling we detected markedly increased levels of the transcription factor SOX11 that has crucial role in embryonic development but is also induced in adults upon tissue injury and cancer." (PMID 35218417, 2022). "3D cultured cells were also shown to have lower levels of genes related to cell proliferation or mitosis (CCNA2, MKI67, and BUB1) and differentiation (ESR1) relative 2D cultured, consistent with higher levels of a cell cycle inhibitor (CDKN1) and cancer stemness–related markers (CD44 and MALAT1)." (PMID 34869246, 2021). "Target prediction and pathway analysis showed that these DNA methylation-dysregulated miRNAs are involved in multiple cancer-related pathways, including cell cycle G1-S growth factor regulation, cytoskeleton remodeling, angiogenesis, EMT, and ESR1-mediated signaling pathways." (PMID 33784351, 2021). "Accordingly, ESR1, ESR2, and PGR may be prognostic biomarkers as well as potential therapeutic targets for a variety of cancer types, necessitating further evaluation." (PMID 34322374, 2021). "ESR1, ESR2, and PGR are potential prognostic markers and therapeutic targets, as well as important factors for the prediction, evaluation, and individualized treatment in several cancer types." (PMID 34322374, 2021). "Together, ESR1, ESR2, and PGR are differentially expressed in multiple cancer types." (PMID 34322374, 2021). "However, the roles of ESR1, ESR2, and PGR in other cancer types have rarely been studied and further investigations are needed to reach a consensus." (PMID 34322374, 2021). "Together, ESR1, ESR2, and PGR isoforms are differentially expressed in different cancer types." (PMID 34322374, 2021). "In our study, we selected ESR1, ESR2, and PGR for an in-depth analysis of mRNA expression, genetic alternations, and clinical outcomes as well as the co-expression of these genes with immunomodulatory factors in a variety of cancer types." (PMID 34322374, 2021). "In case of ESR2 Cr, cancer affected tissue showed a significant negative correlation with ESR1/ESR2 ratio (moderately strong) and positive with both ESR2/PELP1 (very strong) and ESR2/SRC (moderately strong)." (PMID 34207568, 2021). "Considering these results, we hypothesized that genetic alterations in ESR1, ESR2, and PGR play an essential role in cancer progression and combining the expression levels of ESR1, ESR2, and PGR provide prognostic value." (PMID 34322374, 2021). "Additionally, prognostic analysis suggested that ESR1, ESR2, and PGR were significantly correlated with OS and RFS in patients with specific cancer types." (PMID 34322374, 2021). "ESR1 and ESR2 expression have been investigated in many cancer types." (PMID 32536040, 2020). "Finally, we discovered eight genes (MME, SOX17, AGTR1, PGR, ESR1, PAX8, C3 and IRF6) with high amplification frequency compared to other genes across the cancer types." (PMID 31879572, 2019). "Cancer studies have shown that when ESR1 is under-expressed, it fails to activate SP1, resulting in decreased expression of downstream genes that regulate a variety of processes including cell cycle regulation, proliferation, and apoptosis." (PMID 31025158, 2019).
cancer (continued). "Molecular testing in cell lines exhibited that the ESR1 gene was lower expressed in all four EOC cell lines, which could be upregulated by NFE2L2 silencing in the subsequently NFE2L2-downregulated cancer cell lines." (PMID 30597961, 2018). "As an oncogenic factor, ESR1 promotes cell viability and division and plays a role in PCa inflammation; in contrast, ESR2 plays a protective role in PCa development because of its anti-cancer and pro-apoptotic properties." (PMID 30361641, 2018). "To evaluate whether a similar pattern can be observed in cancer cell lines, we selected MCF7 (ER+) and MDA-MB-468 (ER−) cell lines from the CCLE dataset to compare their ESR1 expression levels." (PMID 29688349, 2018). "Differentially expressed genes between the 30 ER-positive and 16 ER-negative cancers were assessed and, as shown, all the three ESR1 probes were classified as highly expressed in ER-positive cancers and were significant on multiple testing (FDR p ≤ 0.001)." (PMID 28697743, 2017). "Malignant tumors with invasive growth of FFPE samples showed significantly lower gene expression of hormone receptors than tumors that were not invasive (ESR1 p = 0.014; PGR p = 0.033; PRLR p = 0.0006; GHR p = 0.011, respectively)." (PMID 27649560, 2016). "IHC demonstrated expression of ESR1 by stromal cells but not epithelial cells (benign or malignant) in untreated samples, but 24% of degarelix-treated cancers stained positive for ESR1 in malignant epithelia compared with 8% of untreated samples." (PMID 26572708, 2016). "In addition, the five genes (JUN, PRKACA, SMAD2, ESR1, and BCL3) shared by the OV and multi-NCA biomarkers form a small network module and are recognized as cancer-related genes." (PMID 26202601, 2015). "Here, we have used a network-based exploration approach to identify a multi-cancer gene expression biomarker highly connected by ESR1, PRKACA, LRP1, JUN and SMAD2 that can be predictive of clinical outcome in 12 types of cancer from The Cancer Genome Atlas (TCGA) repository." (PMID 26202601, 2015). "This trend is clearly illustrated at the DAXX enhancer region in which each CpG within the ESR1-binding site was hypomethylated in luminal A disease compared with normal tissue and luminal B and ESR1-negative cancer." (PMID 26169690, 2015). "Surprisingly, BRCA1 induces the transcription of ESR1 which encodes ERα, and the positive feedback between BRCA1 and ERα provides a rational explanation for why many BRCA1 negative cancers are ERα negative." (PMID 24860786, 2014). "Hypermethylation of the CCND2, ESR1 and WNT5A loci has been reported in various cancer types." (PMID 24586797, 2014). "We have detected aberrant methylation in five cancer-related CpGIs, that is estrogen receptor-α [ESR1 (+244bp)], O6-methylguanine-DNA methyltransferase [MGMT (-463bp)], Wilms' Tumor-1 [WT-1 (-146bp)], Breast Cancer 2 [BRCA2 (+138bp)] and Hermen Antigen [CD44 (+28bp)]." (PMID 22011321, 2011). "These cancers express basal/myoepithelial cell markers such as cytokeratins 5/6, 14 and 17 or vimentin but do not express ESR1, progesterone receptor (PRGR) or ERBB2 (triple negative)." (PMID 19007432, 2008). "The correlation of ESR1 expression with EERES was moderate to high in breast (r = 0.641, P = 7.038e-128) and endometrial (r = 0.413, P = 2.142e-24) cancer patients but low in ovarian (r = 0.226, P = 8.776e-6) and cervical (r = 0.264, P = 3.182e-6) cancer patients." (PMID 38582811, 2024). "ESR1 is a ligand-dependent transcription factor, which can mediate non-genotypic membrane signal pathways to enhance cell proliferation, which is not conducive to the survival of cancer patients." (PMID 38533261, 2024).
cancer (continued). "Notably, well-known cancer-related TFs emerged, such as MYCN, GATA2, and ESR1." (PMID 37370684, 2023). "Hence, CARNIVAL was able to construct a signalling network highly enriched for HER2 signalling, including the signalling proteins MAPKs, ESR1, ERBB2, EGFR, PIK3CA and EP300, which are known to be relevant for the primary mechanism of action of lapatinib in HER2 + cancers." (PMID 37715141, 2023). "Thus, ESR1 and CCDC170 fusion transcript pinpoint cancers with an adverse outcome." (PMID 35151276, 2022). "Hence, in the present study, we investigated the potential of ESR1, ESR2, and PGR as predictive and prognostic biomarkers in multiple cancer types from an immuno-oncological perspective based on bioinformatics analysis to provide a reference for future studies and the application of immunotherapies." (PMID 34322374, 2021). "Thus, RAMP2.AS1/miR-30b-5p/ESR1 and RAMP2.AS1/miR-30b-5p/FOXA1 axes might be involved in the pathogenesis of this kind of cancer." (PMID 34094972, 2021). "Interestingly, positively correlated loci represented cancer driver genes (MYC, PRKCD, RB1, CDK6), molecules involved in immune response (MALT1, PIK3CG), as well as cellular and hormonal signaling (HGF, PTPN13, IGF1, SMAD1, ESR1, CTGF)." (PMID 34368147, 2021). "This reduction in the number of groups (from four subtypes to two classes) suggests that the genes that PAM50 uses to subdivide the more proliferative tumors into luminal B, Her2-enriched and basal-like (ESR1- and ERBB2-associated genes) do not serve that same purpose in a pan-cancer context." (PMID 33396205, 2020). "Thus, we hypothesized that ESR1 and ESR2 might involve in the progression and prognosis of various cancers." (PMID 32536040, 2020). "While we similarly note increased CDK6 expression in our ESR1-mutant models, this did not confer diminished elacestrant antagonism, possibly due to alternate primary resistance mechanisms driving the growth of the cancer cells in our models." (PMID 31852484, 2019). "Our study provides another direction in the clinical use of ESR1 gene: the presence of cancer-specific ESR1 circular isoforms, instead of estrogen receptor 1 protein levels or transcript abundance, might be a potential biomarker for EC diagnosis and progression." (PMID 29464034, 2018). "However, the Comprehensive Cancer Panel is not designed with ESR1 content, so we opted to use ddPCR for concordance testing instead of targeted sequencing for increased sample throughput, lower cost, and higher detection sensitivity." (PMID 30470782, 2018). "Consistent with expectations, canonical luminal genes such as ESR1, GATA3, FOXA1, TFF1 and IGF1R were higher in ER+ samples compared to triple negative samples, while proliferation and mesenchymal genes such as SPRY2, SNAI2, FOSL1, MET and BUB1 were higher in triple negative cancers." (PMID 24520381, 2014). "Therefore, the decreased levels of ESR1 due to 3′UTR pairing with miRNAs differentially upregulated by T. vaginalis and BV bacteria may contribute to exacerbating inflammation-driven comorbidities, cancer, adverse pregnancy outcomes." (PMID 36985125, 2023). "Moreover, data from BC cases with acquired fulvestrant resistance were not available but we hypothesize that expression of ESR1/ERα-LBD would be found in a subset of these cancers." (PMID 35999225, 2022). "It was preliminarily predicted that NR could regulate the targets of CASP3, AKT1,ESR1,ACTB,MAPK3 and may modulate various pathways like estrogen signaling, thyroid hormone signaling pathway, prolactin signaling pathway, proteoglycan in cancer pathway, endocrine resistance pathway." (PMID 36401485, 2022).